AR (androgen receptor)
Diseases named in the same sentence as AR in open-access papers (continued):
Sharing a sentence is not in itself a finding about the gene and the disease.
tumor (continued). "ATAD2 has also been identified as a coactivator of hormone-induced nuclear receptors (oestrogen receptor alpha (ERα) and androgen receptor (AR)), E2Fs, and c-myc for the promotion of tumor progression." (PMID 32462022, 2020). "Despite the lack of dependence of CRPC on androgens, it is widely accepted that AR signaling still drives tumor growth." (PMID 32404918, 2020). "AR, however, was recently reported to have both oncogenic and tumor suppressive roles dependent on the differential expression pattern in different tumor cell types." (PMID 32365531, 2020). "In summary, our data strongly suggest that CAFs induce an upregulation of cholesterol metabolism and steroid biosynthesis in PCa cells, enabling the tumor cells to escape AR targeted therapies." (PMID 31980029, 2020). "This suggests that, although AR mediated transactivation is repressed by antagonists, it leads to the induction of cell senescence and tumor growth inhibition." (PMID 32650419, 2020). "This suggests a dual role of the AR as a tumor suppressor and an oncogene revealing an androgen level-specific opposing tumor response." (PMID 32650419, 2020). "In order to develop effective treatment strategies for patients with each of these cancer types, it is important to understand how AR is functioning similarly and differently to drive tumor growth." (PMID 33062889, 2020). "AR antagonist action results in appearance of NEPC tumour cells, but cytokines such as IL6 which are elevated in PCa patients can also directly induce NED in LNCaP cells." (PMID 32802517, 2020). "We evaluated the advantages and the reliability of novel protocols for the enrichment of tumor extracellular vesicles (EVs), enabling a blood-based test for the noninvasive parallel profiling of multiple androgen receptor (AR) gene alterations." (PMID 32455948, 2020). "Despite the androgen-independent tumor growth of LAPC9, at the gene expression level, the LAPC9 tumor cells do follow AR-responsive patterns (human transcriptomes)." (PMID 33334054, 2020). "Because the LTL331 tumor shows inhibited AR signaling post-castration, we compared the gene expression profile of LTL331_CR_Cells to that from LTL331 tumors 12 weeks after castration." (PMID 32512818, 2020). "Of note, RNAi-mediated down-regulation of AR resulted in upregulation of tumor cell-derived CCL2, and continuous recruitment and enhanced infiltration of macrophages." (PMID 33297508, 2020). "Treatment with either ENZ or ODM potently reduced C4-2-derived spheroid volume suggesting that both AR antagonists inhibit cell proliferation in the 3D spheroid tumor model." (PMID 32562083, 2020). "In the ex vivo analysis of the VCaP tumor samples for effects on the AR signaling pathway, we found a significant reduction of FKBP5 and TMPRSS2 expression after enzalutamide treatment, but no significant changes were seen in the BAY-155 treated study arm." (PMID 31947537, 2020). "This malignant role is due to an aberrant AR cistrome found in tumor cells which activates downstream cancerous pathways." (PMID 32333502, 2020). "It indicates a potential role of this microRNA in mechanisms of suppression of AR expression in this tumor subtype." (PMID 32373367, 2020). "The androgen receptor (AR) expression can interfere with the tumor suppressive effects of TGF-β during early stage of tumor development." (PMID 33076397, 2020). "A newly discovered G4 compound that suppresses AR expression demonstrates selective killing of AR-expressing tumor cells, including CRPC lines." (PMID 32477465, 2020). "Levels of ARV-7 are typically elevated in tumours that also contain elevated levels of full length AR." (PMID 33292167, 2020).
tumor (continued). "Compared to ERhi cases, ERlo cases were associated with larger tumour, higher grade, more necrosis, more sTIL, higher pN stage, high KI67, HER2, EGFR and CK5/6 positivity but PR and AR negativity (p ≤ 0.039)." (PMID 32713939, 2020). "In summary, we provide strong evidence that inhibitors of LSD1 and BRD4 effectively inhibit tumor cell proliferation in high AR-expressing PCa tumors but also increase invasion in this population of PCa cells." (PMID 31901895, 2020). "And, using 2D invasion assays, we show that the inhibition of ESRPs can suppress AR-antagonist-driven tumor invasion." (PMID 32820253, 2020). "T cells infiltration was reported to promote tumor invasion and metastasis via the androgen receptor and estrogen receptor signaling among BLCA patients." (PMID 32117435, 2020). "Targeting IKBKE with small molecule inhibitors in both PC cell line xenografts and patient ex vivo explant models resulted in reduced tumour volume, inhibition of proliferation and reduced AR expression." (PMID 32324216, 2020). "In our study, we discovered that decreased AR expression indicates lymph node metastasis in HER2-positive tumor subtypes." (PMID 32373367, 2020). "A feedback loop in which CAMKK2 is induced by the androgen receptor to maintain this receptor activity and trigger tumor cell proliferation has been proposed during PCa progression." (PMID 32344908, 2020). "A correlation analysis between AR expression and AR-Scores in different tumor stages (American Joint Committee on Cancer staging system) was performed." (PMID 33328560, 2020). "Sex steroid hormones can interact with the cellular receptors estrogen receptor-α (ERα), ERβ, and androgen receptor (AR) and induce gene expression changes, affecting cellular metabolic states, tumor microenvironments, and the immune system." (PMID 32849808, 2020). "Increased CCL5 levels activate hypoxia inducible factor 2α and down-regulate tumor cell androgen receptor signals." (PMID 32630699, 2020). "PCa tumor cells require AR transcriptional activity for survival and proliferation and, thus, PCa therapies block androgen production (androgen deprivation therapy, ADT) or directly inhibit AR activity (anti-androgens)." (PMID 33326447, 2020). "At all stages of PCa development, androgen receptor (AR)-mediated transcription is critical to the growth of the tumor." (PMID 32047165, 2020). "The current study presents the evidence to show that low expression of AR is associated with the development and progression of PTC and AR has tumor suppressive function in the metastasis of PTC." (PMID 32365531, 2020). "Once tumours develop androgen-independent growth, patients are treated with AR pathway inhibitors (ARPI) such as enzalutamide (ENZ)." (PMID 32802517, 2020). "It is possible that the initial tumor growth reduction by therapy with AR antagonist or BAT is due to induction of cellular senescence." (PMID 32351687, 2020). "Taken together, these data not only demonstrated maspin-mediated repression of AR expression to augment epi-drug’s anti-tumor activity but also provided in-depth support for combination treatment strategy with AR antagonist and HDAC inhibitors in CaP therapy." (PMID 33195208, 2020). "The effect of miR-299-3p replenishment on antiproliferative effects was further confirmed in vivo showing decreased tumor volume and tumor progression, and reduced AR and Ki67 expression." (PMID 32198489, 2020). "The tumour sample of this patient was AR+, ER+ and PGR+; the histological subtype was low grade serous and the response lasted for 47 weeks." (PMID 33854564, 2020). "Py-Im polyamide 1, designed to target the consensus androgen response element (ARE) half-site 5’-WGWWCW-3’, has been shown to regulate androgen receptor (AR) and glucocorticoid (GR) driven gene expression in cell culture and suppress tumor growth in vivo." (PMID 33351840, 2020).
tumor (continued). "Androgen receptor (AR) was present in the nucleus of cells throughout DVL3 tumours but was most abundant in clustered regions lining the lumen of glandular structures." (PMID 33003551, 2020). "This explains why the prognostic impact of AR has been shown to be dependent on the molecular subtype of tumour." (PMID 32928183, 2020). "ER+/AR+ tumours showed better OS than ER+/AR- tumours and ER−/AR+ tumours showed worse DFS than ER−/AR- tumours on both univariate and multivariate analysis." (PMID 32928183, 2020). "Overall, AR-pathway activation was able to overcome long-term tumour regression induced by docetaxel treatment." (PMID 32989230, 2020). "Our data suggest that miR-299-3p is frequently downregulated in PCa cells and tissues and exerts a tumor suppressor role through the bimodal targeting of AR and VEGFA to inhibit different signaling cascades that are constitutively active in PCa." (PMID 32198489, 2020). "LNCaP cells are an AR positive, androgen sensitive cell line derived from metastatic lymph node PCa tumours." (PMID 32802517, 2020). "AR is a potential therapeutic target considering 10–40% of TNBC express AR of 1 to 10% of stained tumor cells." (PMID 32486021, 2020). "Secondly, several previous researches have demonstrated the interplay between ZEB1 and AR signaling in various tumor types 9,20,21." (PMID 32153739, 2020). "The mechanism by which galeterone induces tumour apoptosis is not fully understood, but it has been shown to act as a multi-targeting agent disrupting AR signalling." (PMID 33303035, 2020). "Estrogen Receptor Alpha (ERα) promotes BCa tumor growth and Androgen Receptor (AR) promotes PCa tumor growth; thus, patients are treated with HR-targeting therapies." (PMID 31959131, 2020). "In summary, these studies support the notion that JQ1 inhibits tumor growth but induces metastasis in high AR-expressing PCa cells." (PMID 31901895, 2020). "In TNBC, AR is reported to interact with androgen response elements (AREs) and stimulate tumor cell growth in an androgen-dependent manner." (PMID 33213491, 2020). "AR+ luminal cells form the bulk of the primary PCa tumor and require AR transcriptional activity for survival and proliferation; thus, PCa therapies block androgen production (androgen deprivation therapy, ADT) or directly inhibit AR activity (anti-androgens)." (PMID 33326447, 2020). "Similar effects were observed in vivo where there was a significant reduction in tumor volume and a delay to tumor doubling and tripling times in mice with AR+ TNBC xenograft tumors treated with seviteronel and radiation." (PMID 32117061, 2020). "This important finding suggests the significant role of the co-regulators in the AR mediated tumor progression in AR (+) TNBC patients." (PMID 32778063, 2020). "In a subset of ten patients, we had access to corresponding plasma samples, which were analyzed by sWGS, i.e., plasma-Seq, to call for focal AR amplifications and to quantify tumor content in cell-free DNA using the probabilistic ichorCNA model." (PMID 32796730, 2020). "Considering the prostate PDX models, 10 were established from biopsies prior to anti-androgen receptor treatments and 6 from anti-androgen receptor resistant tumours, and in one case, paired pre and post-treatment PDX models were developed." (PMID 32964129, 2020). "miR-1 acts as a tumor suppressor that is involved in regulating BM, and miR-1 is tightly regulated by the AR." (PMID 32443915, 2020). "Our data strongly suggest that taxane efficacy can be optimised by maintaining suppression of testosterone levels in order to minimise interference with docetaxel tumour accumulation and block AR-driven prosurvival signalling." (PMID 32989230, 2020). "Recently, some studies have been devoted to assessment of the role of AR in GC as a male-predominant tumor 17,18." (PMID 32153739, 2020).
tumor (continued). "Testosterone impaired docetaxel antitumour activity through two different modes of action: interference with docetaxel tumour accumulation, thereby reducing tubulin stabilisation and AR-pathway activation protecting cells from docetaxel-induced cell death." (PMID 32989230, 2020). "Rather, there is crosstalk between EGFR and AR, and treatment with bicalutamide decreases xenograft tumor growth." (PMID 33062889, 2020). "In contrast, a recent study has shown that AR mRNA and protein expression is higher in metastatic tumor tissues than in primary tumors and increases with tumor stage and Gleason score." (PMID 32292603, 2020). "Androgen receptor (AR) blockade evasion is the most common form of therapeutic resistance in PCa and represents an example of tumor adaptation that develops uncontrolled castration-resistant clones." (PMID 33291528, 2020). "For the cohort of early-stage MBC patients, outcome as overall survival (OS), univariate, there was significant difference in OS depending on age at diagnosis, tumor size, lymph node status, tumor “type and grade” as well as subtype, PR and AR." (PMID 32108307, 2020). "In line with this idea, pharmacological inhibition of the mitochondrial pyruvate carrier has recently been demonstrated to specifically impair AR-driven tumour growth." (PMID 32427840, 2020). "Androgen deprivation therapy (ADT), both surgical and biochemical, is the standard of care in metastatic castration-sensitive prostate cancer (mCSPC), owing to the driving role of androgen receptor (AR) in the growth of this tumour." (PMID 35582226, 2020). "16α-[18F]fluoro-17β-estradiol ([18F]FES) and 16β-[18F]fluoro-5α-dihydrotestosterone ([18F]FDHT) PET/CT allow visualization, respectively, of estrogen (ER) and androgen receptor (AR) status in tumor lesions." (PMID 32722205, 2020). "The dual role of AR as either a suppressor or inducer of tumor progression enables both androgens and antiandrogens to be used in potential therapeutic regiments." (PMID 31952272, 2020). "The aim of these therapies is to decrease male hormone levels and AR signaling activation, since this axis is promoting tumor progression." (PMID 32714315, 2020). "Curcumin also shows positive outcomes when tested in animal models, where it delays the tumour growth and suppresses AR expression in ADPC (LNCaP) xenograft model." (PMID 32131560, 2020). "We found that AR suppressed PD-L1 transcription, directly altered the tumor microenvironment by decreasing the membrane PD-L1 expression and enhance the function and proliferation of activated CD8+ T cells." (PMID 32579541, 2020). "The fact that there are multiple mechanisms by which AR activity is maintained in the presence of low levels of androgen gives rise to a molecularly diverse group of CRPC tumour cells, even within the one patient." (PMID 33292167, 2020). "It was well documented that the AR antagonist enzalutamide or HDAC inhibitor MS-275 possessed anti-tumor activity." (PMID 33195208, 2020). "Our in vitro and in vivo data suggest that treatment with CCG1423 inhibits AR translocation to the nucleus with decrease in cell viability, tumour volume and PSA." (PMID 33260953, 2020). "In summary, we demonstrated that KLF5 is crucial for androgen/AR signaling to activate the transcription of specific genes, including some that mediate cell proliferation, and to promote cell proliferation and tumor growth in PCa cells." (PMID 32245249, 2020). "All the cases in the present series showed positive immunostaining for AR in the primary tumor but up to 29.6% of them achieved in the last contact a castration-resistant status." (PMID 33291528, 2020). "Endothelial cells, by secreting CCL5, also inhibit androgen receptor signaling and promote tumor cell invasion." (PMID 32630699, 2020). "AR signaling has been shown to be important for control of cell cycle-related gene expression, resulting in growth implications in tumor cells." (PMID 33062889, 2020).
tumor (continued). "Lastly, AR activity is dependent not only on AR but also on the expression of AR synthesizing enzymes in tumor tissues." (PMID 32850312, 2020). "It has been shown that the level of the androgen receptor (AR) gene expression in tumor tissue is closely related to anti-androgen treatment sensitivity." (PMID 33324566, 2020). "Specifically, KLF5 silencing significantly attenuated the functions of AR in the maintenance of colony and sphere formation in vitro and xenograft tumor growth in nude mice." (PMID 32245249, 2020). "Western blot and immunohistochemistry assays of mice tumor specimens showed decreased AR and Ki67 expression in LINC00675-depleted tumors." (PMID 32801300, 2020). "The PCa cells have the ability to dedifferentiate into CSCs exhibiting tumor-initiating potential with an invasive phenotype and resistance to AR-antagonists." (PMID 32754615, 2020). "There were statistically significant associations between OS and age at diagnosis, lymph node status, tumor size and AR status." (PMID 32108307, 2020). "ER-negative/AR-positive (ER−/AR+) tumours (p = 0.014) had a worse DFS than ER-negative/AR-negative (ER−/AR-) tumours." (PMID 32928183, 2020). "Hormonal receptor status of tumour tissue was subsequently tested centrally; 29/40 (72.5%) patients were AR+ (>10% staining tumour cells) (two samples unavailable), 35/37 (95%) ER+ and 25/37 (68%) PGR+ (five samples undetermined)." (PMID 33854564, 2020). "Taken together, the data not only demonstrated maspin-mediated repression of AR to augment drug anti-tumor activity but also provided in-depth support for combination of HDAC inhibitors with AR antagonist in CaP therapy." (PMID 33195208, 2020). "The high AR expression group showed a higher proportion of patients with a tumor size ≤2 cm, a positive ER, a positive PR, a positive HER2, and a low histologic grade when compared with the low AR expression group." (PMID 32290220, 2020). "DNA-PKcs is found at regulatory elements bound by the AR and stimulates its activity, thus eliciting changes in the transcriptional program and enhancing tumor progression." (PMID 33158305, 2020). "Although ichorCNA tumor fractions were below the quantitative threshold of 3% in 30% of the patients (3/10), AR amplicons were identified in 50% of the patients (5/10), which is in range with previous findings in advanced PC." (PMID 32796730, 2020). "Analysis of tumor tissues showed a higher expression of miR-299-3p, and reduced expression of AR and Ki67 proliferation marker in the doxycycline treated groups compared to the uninduced group." (PMID 32198489, 2020). "The pejorative prognostic value of Sox2 was confirmed by multivariate survival analysis (HR = 1.48, 95% CI 1.02–2.15, p = 0.0420), with tumor size, ER and AR as the covariates (p < 0.0001, Cox proportional-hazard regression)." (PMID 33553286, 2020). "Androgen receptor (AR) amplification is conserved between CTCs and tumor biopsies in patients with metastatic CRPC, and CTCs can serve as a non-invasive surrogate to document AR amplification." (PMID 33266262, 2020). "The pleiotropic effects exerted by tumor suppressor miRNAs include the modulation of androgen receptor (AR) genes expression (miR-488 *, miR-125b, miR-155a, miR-27a) and cell proliferation stimulation (miR-497, miR-296-5p)." (PMID 32268584, 2020). "In conclusion, it seems that AR has pro-tumor properties by promoting proliferation, migration and invasion of tumor cells." (PMID 33266110, 2020). "One week after host castration, tumor growth slowed, and AR expression markedly decreased, indicating reduced AR transcriptional activity." (PMID 32092044, 2020). "This was confirmed by multivariate analysis, as Sox2 was associated with higher probabilities of distant metastasis (HR = 2.01, 95% CI 1.08–3.75, p = 0.0288), independently of tumor size and AR expression (p = 0.0021, Cox proportional-hazard regression)." (PMID 33553286, 2020).